SIRT2 (sirtuin 2)
Diseases named in the same sentence as SIRT2 in open-access papers (continued):
Sharing a sentence is not in itself a finding about the gene and the disease.
tumor (continued). "H&E staining of tumor tissues showed that SIRT2 knockdown group had a complete envelope of tumors, while the tumor envelope was disrupted in the control group, indicating that SIRT2 knockdown inhibited tumor invasiveness." (PMID 36344502, 2022). "SIRT2 is considered to be a tumor suppressor, and under stress conditions can induce cell senescence or apoptosis." (PMID 35267521, 2022). "Although there are potentially two opposing roles of SIRT2 as a tumor suppressor and a promotor, there is increasing evidence that overexpression of SIRT2 significantly inhibits CRC proliferation, migration, and invasion." (PMID 35326523, 2022). "As a tumour-promoting factor, SIRT2 mainly promotes the immune escape of tumour cells by inducing immune avoidance, improving energy metabolism, and changing the tumour microenvironment, thereby inducing the development of tumours." (PMID 36101744, 2022). "It has been shown that SIRT1, SIRT2, SIRT3, SIRT4, or SIRT6 deletion causes tumor development in an animal model of cancers." (PMID 36358687, 2022). "In contrast to previous results suggesting a broad tumor-promoting effect for SIRT2, our study indicated that SIRT2 expression was decreased in DTC tissues compared to the nontumorous tissues." (PMID 35136826, 2022). "More interestingly, the infiltration levels of most of these immune cells above were strongly correlated to the expression of SIRT2 in tumor tissues of LUAD patients." (PMID 36844923, 2022). "Our initial screening of tumor-infiltrating leukocytes revealed a difference only in the number of NK cells while T cells, and B cells were similar between WT and Sirt2-KI mice." (PMID 34155309, 2021). "Together, these data illustrate a novel inhibitory role of systemic SIRT2 on NK cell function resulting in tumor progression promotion." (PMID 34155309, 2021). "Although SIRT2 was initially reported to be a tumor suppressor, as Sirt2 knockout mice developed more tumors than wild-type mice as they age." (PMID 34650436, 2021). "In this study we strove to provide evidence that NK cell is a mediator of SIRT2’s effect in tumor progression." (PMID 34155309, 2021). "Mechanistically, systemic overexpression of SIRT2 reduces the number of tumor-infiltrating natural killer (NK) cells and suppresses NK cell function and proliferation within the tumor microenvironment (TME)." (PMID 34155309, 2021). "We further demonstrated mice overexpressing SIRT2 show enhanced tumor progression as well as decreased NK cell infiltration and functional activity within the tumor." (PMID 34155309, 2021). "Immunohistochemistry staining of tumors from Sirt2-KI and WT mice was also performed to further evaluate NK cell proliferation within the tumor microenvironment." (PMID 34155309, 2021). "With this study, we sought to further explore the complex relationship between SIRT2 and tumor progression." (PMID 34155309, 2021). "In this study, SIRT2-overexpressing mice exhibited enhanced tumor growth and larger tumor volumes compared to their wild-type littermates." (PMID 34155309, 2021). "The data compiled from this study reveals a potential mechanism explaining systemic SIRT2’s impact upon tumor progression based on suppression of NK cell function within the tumor microenvironment." (PMID 34155309, 2021). "Studies have demonstrated that SIRT1 and SIRT2 can raise the capacity of tumor cells to break through the membrane, letting tumor cells get extremely transformed and so much invasive capacity." (PMID 33705642, 2021). "Lastly, pharmacological inhibition of SIRT2 increases NK cell tumor infiltration and suppresses allograft melanoma tumor growth." (PMID 34155309, 2021). "We are identifying a novel relationship between SIRT2 and NK cells in the promotion of tumor progression." (PMID 34155309, 2021). "Altogether, our data demonstrate a novel role for systemic SIRT2 expression on NK cell function and tumor progression." (PMID 34155309, 2021).
tumor (continued). "SIRT2’s effect on NK cells was further characterized using NK cells harvested from the spleens of non-tumor-bearing mice so that a potential effect on NK cell function from tumors would be eliminated." (PMID 34155309, 2021). "Conversely, some studies propose that SIRT1 and SIRT2 themselves can attend as a tumor suppressor, at least in particular circumstances." (PMID 33705642, 2021). "SIRT2’s impact on NK cells within the tumor microenvironment invokes the need for additional studies examining SIRT2’s effects on other NK cell processes such as maturation, migration, and cytotoxic properties as these issues are not currently characterized." (PMID 34155309, 2021). "It is also known that SIRT1 and SIRT2 proteins play an important role in the tumor cells, especially during chemotherapy." (PMID 33705642, 2021). "While, SIRT2 is regarded as one of the dominant targets for the anti-tumor cell proliferative action of DUb." (PMID 35177983, 2021). "In recent years, SIRT2 has been described as both a tumor suppressor and oncogene with divergent expression and function in various malignancies." (PMID 34155309, 2021). "Both WT and Sirt2-KI mice had tumor formation rates of 100%; however, Sirt2-KI mice developed tumors that were growing significantly faster than those harvested from WT mice." (PMID 34155309, 2021). "Although genetic studies tend to suggest that SIRT2 is a tumor suppressor, pharmacological studies suggest the opposite." (PMID 33014852, 2020). "NAD+-dependent deacetylase SIRT2 is extensively involved in tumor progression, playing drastically different roles in various tumor models, dictated by the substrate(s) of SIRT2 deacetylase activity 27, 34-36." (PMID 32104503, 2020). "SIRT2 has been shown to provide anti-tumor potential by deacetylating both CDC20 and CDH1 to promote their recruitment to the APC and cell cycle progression." (PMID 32805721, 2020). "The Matrigel Transwell invasion assays consistently showed similar results regarding the role of HRD1 and SIRT2 in the tumor invasion of A549 and H446 cells." (PMID 31932479, 2020). "While SIRT2 is a well-known deacetylase, acetylation is also involved in the mechanism of regulating tumor immune responses." (PMID 33061819, 2020). "Another potential mechanism is that SIRT2 induces enrichment of CD8+ TEM in PBMCs by affecting key signaling pathways of tumor immune system." (PMID 33061819, 2020). "In contrast, SIRT2 down‐regulation in SW480 cells significantly enhanced the number of migrating or invading tumour cells compared with the number of migrating and invading control cells." (PMID 32697380, 2020). "For tumorigenesis assays, the subcutaneous injection of cells that stably expressed SIRT2, shSIRT2 or their controls into the flanks of nude mice was followed by monitoring tumour volumes." (PMID 32697380, 2020). "SIRT2 overexpression was found to restore the tumour‐suppressive effects of miR‐212‐5p up‐regulation." (PMID 32697380, 2020). "Silencing SIRT2 significantly suppressed tumor angiogenesis by inhibiting the STAT3/VEGFA signaling pathway in CRC cells." (PMID 31974361, 2020). "The results demonstrated the up‐regulation of miR‐212‐5p in CRC tumour tissues relative to normal tissues, which is in contrast to the expression of SIRT2." (PMID 32697380, 2020). "In non–small‐cell lung cancer cells, SIRT2 inhibits tumour growth by impairing Skp2‐mediated p27 degradation." (PMID 32697380, 2020). "Taken together, our study revealed the novel findings that tumour‐suppressive SIRT2 is a direct functional target gene of miR‐212‐5p and that the miR‐212‐5p/SIRT2 axis is a promising prognostic factor and potential therapeutic target in CRC." (PMID 32697380, 2020). "In vivo, we found that SIRT2 overexpression significantly suppressed tumour growth, whereas SIRT2 inhibition promoted tumour growth." (PMID 32697380, 2020).
tumor (continued). "In summary, our study demonstrates that SIRT2 plays an important tumour‐suppressive role in CRC progression and serves as a promising diagnostic or prognostic biomarker, clinical predictor and therapeutic target for CRC diagnosis and treatment." (PMID 32697380, 2020). "Taken together, these results suggest that SIRT2, targeted by miR‐212‐5p, acts as a tumour suppressor in CRC and that the miR‐212‐5p/SIRT2 axis is a promising prognostic factor and potential therapeutic target in CRC." (PMID 32697380, 2020). "Contrarily, NOTCH signaling pathway increased ALDH1A1 Lys-353 deacetylation at a post-translational level through the induction of silent information regulator 2 (SIRT2) expression, promoting tumorigenesis and tumor growth in a BC model." (PMID 33584277, 2020). "Sirt2, similarly to Sirt1, also has a regulatory function, and it has been suggested that it can act both as a tumor promoter and as a tumor suppressor." (PMID 33203121, 2020). "Sirt2 has been discussed as an anticancer target but also tumor suppressive activities of Sirt2 have been mentioned." (PMID 32426286, 2020). "In contrast to SIRT2, a positive correlation was found between miR‐212‐5p up‐regulation and tumour differentiation, metastasis and the AJCC stage." (PMID 32697380, 2020). "There are two opposing viewpoints that support SIRT2 functioning as an oncogene and a tumor suppressor." (PMID 33014852, 2020). "Taken together, these in vivo findings confirm that SIRT2 acts as a tumour suppressor of CRC cell metastasis and growth." (PMID 32697380, 2020). "For example, SIRT2 was reported to be downregulated in liver cancer tissues as compared with normal tissues, suggesting its possible role as a tumor suppressor." (PMID 33207824, 2020). "The relationship between mRNA expression levels of SIRTs and different tumor stages of OC were also analyzed, and they were all significantly upregulated in stage II except for SIRT2 and SIRT4." (PMID 31572453, 2019). "Sirt2 protein expression was significantly higher in tumor tissues compared with adjacent normal lung tissues." (PMID 31324785, 2019). "This correlates with a more aggressive tumor, shorter time to relapse and death, highlighting the oncogenic role of SIRT2." (PMID 30761005, 2019). "Similar to SIRT1, the impact of SIRT2 on cell viability appears to depend on the cellular context or the kind of tumor." (PMID 31817470, 2019). "The observed effect is consistent with previous studies showing that SIRT2 functions as a tumor suppressor." (PMID 31970087, 2019). "We further showed that the function of SIRT2 in tumour angiogenesis was dependent on the STAT3/VEGFA signalling pathway in CRC cells." (PMID 30584257, 2018). "Increasing evidence has demonstrated that SIRT2 plays important roles in tumourigenesis and tumour progression." (PMID 30584257, 2018). "Similar to the findings for STAT3, we found in this work that inhibition of SIRT2 significantly attenuated tumour angiogenesis under normal culture conditions." (PMID 30584257, 2018). "Taken together, these data strongly indicate that inhibition of SIRT2 abolished tumour-induced angiogenesis." (PMID 30584257, 2018). "SIRT2 is also involved in tumour metabolism regulation through MYC stabilization by deacetylating H4K16ac." (PMID 30356832, 2018). "Several results suggested that the role of SIRT2 in tumour angiogenesis is dependent on the STAT3/VEGFA signalling pathway." (PMID 30584257, 2018).
tumor (continued). "Recently, emerging reports have indicated that SIRT2 plays critical roles in proliferation, metastasis and tumourigenesis in diverse tumours." (PMID 30584257, 2018). "To investigate the potential role of VEGFA in SIRT2-mediated tumour angiogenesis, we evaluated the migratory ability of HUVECs incubated with CM from ShSIRT2 SW480 cells and stimulated with VEGFA." (PMID 30584257, 2018). "SIRT2 has an essential role in maintaining the integrity of mitosis and has been proposed to act as a tumor suppressor by preventing chromosomal instability during mitosis." (PMID 30081901, 2018). "Previous studies have demonstrated that the role of SIRT2 in tumour progression is dependent on the context of tissue type." (PMID 30584257, 2018). "Although important in regulating the cell cycle, the role of SIRT2 in tumorigenesis is unclear due to contradictory reports of SIRT2 knock out mice presenting with spontaneous tumors and SIRT2 inhibition prolonging tumor progression." (PMID 30216989, 2018). "To further confirm the role of SIRT2 in tumour angiogenesis, we created a xenograft model in nude mice via the subcutaneous injection of ShNC SW480 cells or ShSIRT2#1 SW480 cells." (PMID 30584257, 2018). "Regarding SIRT2, both oncogene or tumour suppressor functions have been suggested, depending on the tumour context." (PMID 30356832, 2018). "In another study, the tumor suppressor SIRT2 has been found to interact with and degrade AURKA, partially accounting for the observation that Sirt2-deficient male mice would develop more HCC than wild-type mice." (PMID 28903390, 2017). "In this dataset, a correlation between decreasing SIRT2 and increasing P300 mRNA expression occurs in tumor samples (R = −0.46)." (PMID 29262808, 2017). "Among the seven known mammalian Sirtuins, SIRT2 can function as a tumor suppressor and its knockdown has been shown to induce gender-specific tumorigenesis in mice." (PMID 29262808, 2017). "In particular, the inhibition of tubulin deacetylation mediated by two identified tubulin deacetylases HDAC6 and SIRT2 enhances sensitivity to the anti-motility activity of paclitaxel theoretically potentiating the anti-tumor effect of the drug." (PMID 28423567, 2017). "Experiments using knockout SIRT2 in mice showed that SIRT2 is a tumor suppressor through its role in regulating mitosis and genome integrity." (PMID 28514749, 2017). "SIRT2 mRNA expression levels are significantly lower in primary tumor (p = 0.01) and metastasis (p = 0.004), compared to benign prostatic tissues." (PMID 29262808, 2017). "Although additional studies further support the tumor-suppressive role of SIRT2, it is worth mentioning that SIRT2 has been shown to exert dual functions where it seems to have oncogenic properties as well." (PMID 27637077, 2016). "SIRT2 is a histone deacetylase that is ubiquitously expressed in normal tissues, but get lost in many primary human tumors and tumor cell lines." (PMID 26942878, 2016). "Here, we demonstrate that SIRT2 functions as a tumor suppressor in the context of KRAS-dependent tumorigenesis." (PMID 27637077, 2016). "Given the fact SIRT2 maintains genomic stability this sirtuin mainly functions as a tumor suppressor." (PMID 27916001, 2016). "In particular, 2 months after adenoCRE administration, the Sirt2-/--KrasG12D mice lungs exhibited increased numbers of tumor cell nests per 10x field and increased tumor size." (PMID 27637077, 2016). "SIRT2 inhibitors exhibit anti-tumour effects by promoting apoptosis and inhibiting cell growth in cancer." (PMID 26091232, 2015). "High SIRT1 and SIRT2 protein levels were found in NSCLC cell lines compared with non-tumor lung epithelial cells." (PMID 25915617, 2015). "SIRT2 is a tumor suppressor gene that has an essential role in maintaining the integrity of mitosis by positively regulating the activity of anaphase-promoting complex/cyclosome." (PMID 25486244, 2014).
tumor (continued). "It is worth noting that SIRT2 has been identified as a tumor suppressor, while c-Myc is a prominent oncogene that promotes tumor cell proliferation and tumor vascularization." (PMID 24940000, 2014). "SIRT2 expression in the tumor was significantly downregulated with the increased drug dosage." (PMID 40166471, 2025). "The SIRT2 protein plays key roles in tumor-promoting and tumor-suppressing functions." (PMID 40933952, 2025). "SIRT2 promotes tumor angiogenesis by regulating STAT3/VEGFA pathway." (PMID 40746889, 2025). "By modulating the SPOP-SIRT2 interaction or enhancing SPOP activity, it may be possible to restore the degradation of SIRT2, thereby inhibiting tumor progression." (PMID 40521202, 2025). "However, SIRT2 is expressed in non–β cells and is an important tumor suppressor in some cell types, underscoring the need for a high degree of cell-type selectivity were SIRT2 to be therapeutically inactivated." (PMID 40762838, 2025). "Moreover, they showed that inclusion of the SIRT2 inhibitor had a synergistic suppressing effect on tumor growth and increased survival in a murine model." (PMID 40149343, 2025). "Interestingly, the tumor suppressor Fn14 was shown to inhibit SIRT2’s pro-metastatic activity by physically interacting with it and blocking its nuclear translocation, thereby facilitating Slug degradation and suppressing metastasis." (PMID 41471349, 2025). "From a mechanistic point of view, metformin can reduce histone acetylation at the CCR8 promoter and inhibit CCR8 expression on tumor-infiltrating Treg cells by upregulating AMPK-activated Sirtuin 2 (SIRT2), thus enhancing the effectiveness of anti-PD-1 immunotherapy." (PMID 39944825, 2025). "Critically, chronic Holdemania overabundance may reshape the tumor microenvironment via TGF-β1/SIRT2 signaling, driving fibroblast activation and collagen deposition, a mechanism implicated in premetastatic niche formation." (PMID 40510587, 2025). "Conversely, SIRT2 is a tumor suppressor in CRC and is repressed by miR-212-5p." (PMID 41425553, 2025). "SIRT2 has also been described as both an oncogene and a tumor suppressor." (PMID 40710366, 2025). "In this study, we demonstrated that SIRT2 plays tumor suppressive role in PC." (PMID 38216561, 2024). "Similarly, an in vivo study conducted with mice bearing C6 glioma with exposure to SIRT2-NBs US (+) resulted in a significant reduction in tumor growth." (PMID 39335153, 2024). "Therefore, SIRT2 holds potential value in enhancing the anti-tumor effects mediated by liver NK cells." (PMID 38962006, 2024). "Moreover, these publications demonstrate the ability of SIRT2 inhibition to impede the metastasis of xenograft tumours, highlighting the potential for AGK2 treatment to achieve a similar outcome." (PMID 39682770, 2024). "For example, the expression of HDAC2/3/7/10 and SIRT2/3/6/7 associates with tumor size in BRCA, the level of HDAC4/5/8/10/11 and SIRT1/5/7 associates with tumor size in KIRC, and the upregulation of HDAC2/4/6/7 and SIRT1/2/6 associates with tumor size in LUAD." (PMID 39063083, 2024). "Moreover, we demonstrated SIRT2 deletion in Panc-1 cells inhibited the growth of xenografted tumor in mice, revealing a significantly reduction in tumor weights and volumes." (PMID 38216561, 2024). "Finally, we investigated the tumour‐promoting effect and molecular mechanism of Sirtuin 2 (SIRT2)‐mediated ACLY deacetylation in ESCC." (PMID 38426936, 2024). "Furthermore, overexpression of SIRT2 enhances the secretion of pro-inflammatory cytokines and cytotoxic granules by NK cells, thereby exhibiting increased anti-tumor activity." (PMID 38962006, 2024). "To test this, we employed RNA-seq to profile HCC tumor tissue from Sirt2+/+ and Sirt2−/− mice." (PMID 37628798, 2023).